THRB (thyroid hormone receptor beta)
Description:
Nuclear hormone receptor that can act as a repressor or activator of transcription. High affinity receptor for thyroid hormones, including triiodothyronine and thyroxine.
Synonyms: ERBA2; NR1A2; THR1; THRB1; THRB2; ERBA-BETA; GRTH; TRbeta; TRb; c-erbA-beta; c-erbA-2; THRbeta; TRbeta1; THRbeta1; Thrbeta2; PRTH
Tractability: Small molecule: an approved drug acts on it; a structure with a bound ligand is known; a high-quality ligand is known; it has a high-quality binding pocket; it belongs to a druggable protein family. PROTAC: a small molecule that binds it is known.
Target class: Nuclear hormone receptor subfamily 1; Nuclear hormone receptor subfamily 1 group A; Transcription factor; Nuclear hormone receptor subfamily 1 group A member 2; Nuclear receptor
Chemical probes: CHEMBL125946, MB07344, ML151
Gene: Protein-coding gene on chromosome 3 (24,117,153 to 24,495,756, reverse strand). Ensembl gene ENSG00000151090.
Subcellular location: Nucleus
Subcellular location (Human Protein Atlas): Nuclear bodies
Pathways (Reactome):
Gene expression (Transcription): Nuclear Receptor transcription pathway
Metabolism of proteins: SUMOylation of intracellular receptors
Gene Ontology:
Molecular function: enzyme binding; nuclear receptor activity; protein binding; sequence-specific double-stranded DNA binding; thyroid hormone binding; transcription coactivator binding; DNA binding; DNA-binding transcription factor activity; DNA-binding transcription factor activity, RNA polymerase II-specific; RNA polymerase II cis-regulatory region sequence-specific DNA binding; chromatin binding; chromatin DNA binding; sequence-specific DNA binding; zinc ion binding
Biological process: cellular response to thyroid hormone stimulus; mRNA transcription by RNA polymerase II; positive regulation of thyroid hormone receptor signaling pathway; positive regulation of transcription by RNA polymerase II; cell differentiation; DNA-templated transcription; negative regulation of transcription by RNA polymerase II; retinoic acid receptor signaling pathway; thyroid hormone receptor signaling pathway; regulation of DNA-templated transcription
Cellular component: nuclear body; RNA polymerase II transcription regulator complex; chromatin; nucleoplasm; nucleus
Genetic constraint (gnomAD): Loss-of-function variants: 12 observed, 45.19 expected, observed/expected ratio (o/e) 0.27, 90% interval 0.17 to 0.43. The upper end of that interval is the gene's LOEUF score, 0.43, which puts it in group 1 of 6, group 1 being the genes least tolerant of losing a copy. Missense variants: 329 observed, 572.44 expected, observed/expected ratio (o/e) 0.57, 90% interval 0.52 to 0.63. Synonymous variants: 201 observed, 206.52 expected, observed/expected ratio (o/e) 0.97, 90% interval 0.87 to 1.09.
Homologues: Orthologues: dog THRB (82% identical), rabbit THRB (82% identical), chimpanzee THRB (81% identical), pig THRB (81% identical), rat Thrb (81% identical), guinea pig THRB (81% identical), mouse Thrb (81% identical), macaque THRB (79% identical), tropical clawed frog thrb (77% identical), zebrafish thrb (76% identical), Drosophila melanogaster Hr96 (19% identical), Caenorhabditis elegans nhr-114 (18% identical), and 179 more. Paralogues in human: THRA (60% identical), RARB (28% identical), RARG (27% identical), RARA (27% identical), NR1D2 (27% identical), RORA (26% identical), RORC (26% identical), NR1H4 (25% identical), VDR (25% identical), NR1D1 (24% identical), NR1H3 (24% identical), RORB (24% identical), and 6 more.
Diseases named in the same sentence as THRB in open-access papers:
THRB is named in the same sentence as 129 diseases in open-access papers, as found by Europe PMC text mining. Sharing a sentence is not in itself a finding about the gene and the disease. The quoted sentences say what the papers report.
Hepatic steatosis (24 papers, 2020 to 2026). Steatosis is a term used to denote lipid accumulation within hepatocytes. "By targeting pathophysiological processes within the liver, thyroid hormone receptor beta (THR-β) agonists such as resmetirom are essential for the treatment of metabolic dysfunction associated with hepatic steatosis." (PMID 40136408, 2025). "Studies have provide evidence that impairments in intrahepatic TRb signaling due to mutations of the THRB gene can lead to hepatic steatosis, which emphasizes the influence of TH in the liver metabolism of lipids." (PMID 36300106, 2022). "provided evidence that impairments in liver TRβ signaling due to mutations in the THRB gene can lead to hepatic steatosis, which indicates the influence of TH on lipid metabolism in the liver." (PMID 36300106, 2022). "Its activation, through a highly liver selective THRb agonist (resmetirom), is associated with liver steatosis and inflammation reduction." (PMID 34199535, 2021). "Relevant findings suggest that the intrahepatic impairment of the thyroid hormone (TH) pathway due to thyroid hormone receptor beta (THRB) gene mutations may lead to fatty liver; TH resistance can thus take part in NAFLD development." (PMID 37233622, 2023). "The main thyroid hormone receptor (THR) expressed in the liver is THRβ and its role was demonstrated in a study designed with mice, where a dominant negative mutation in THRβ was analyzed and it was observed that these mice developed hepatic steatosis in a few months." (PMID 33805893, 2021). "Indeed, resmetirom, a selective thyroid hormone receptor beta (THRβ) agonist, has recently been approved for treatment of liver fibrosis, and more THRβ agonists are currently in phase 2-3 clinical trials for use in metabolic dysfunction-associated fatty liver disease." (PMID 42118980, 2026). "Research shows that the impaired signaling of thyroid hormone (TH) and thyroid hormone receptor beta (TRβ) in the liver can trigger hepatic steatosis." (PMID 40137541, 2025). "Consistently, THRβ-specific agonist was found to reduce hepatic steatosis and improve hepatic IR in rats." (PMID 41040505, 2025). "Resmetirom is a new promising agent against MASLD; it is an oral drug, which is liver-directed, and is a thyroid hormone receptor beta (THR-β)-selective agonist in development for the treatment of hepatic steatosis with liver fibrosis." (PMID 39596967, 2024). "In summary, our study reveals a complex time-of-day dependent interaction of different TH-related signals in the regulation of liver physiology indicating an opportunity for chronopharmacological approaches to TH/THRB manipulation in fatty liver diseases." (PMID 40603776, 2024). "Although previous studies have already demonstrated the effectiveness of several THRβ agonists in reducing hepatic steatosis in animal models, the effect of THRβ-selective thyromimetics on the regression of preneoplastic lesions remained largely unexplored." (PMID 36910628, 2023). "In the present study, we investigated the effect of a novel halogen free THRβ-selective agonist TG68 on hepatic steatosis and regression of preneoplastic lesions in rats exposed to DEN and HFD." (PMID 36910628, 2023). "Recently, THRβ agonists were found to be effective for the prevention and treatment of hepatic steatosis and NASH." (PMID 36503486, 2022). "For example, Resmetirom (MGL-3196), a THRβ agonist, significantly improved hepatic steatosis in NASH patients and ameliorated the progression of liver fibrosis in mice with advanced NASH without affecting body weight." (PMID 36503486, 2022). "Resmetirom, a thyroid hormone receptor beta (THR-β) agonist, has recently been approved by the US FDA as the only pharmaceutical therapy for fatty liver disease." (PMID 39850574, 2024). "Thyroid hormone receptor-beta (THR-β) agonists, which lower triglycerides and cholesterol while conferring hepatic benefits, had emerged as a primary strategy for addressing dyslipidemia, obesity, and hepatic steatosis." (PMID 40904774, 2025).
liver fibrosis (21 papers, 2022 to 2026). "Newly-developed thyroid hormone receptor beta (THR-β)-selective agonist Resmetirom nicely suppressed human liver fibrosis in 25% of MASH patients, while it caused severe diarrhea and nausea in 10% of patients." (PMID 39920308, 2025). "A notable example is the recently approved Resmetirom, a thyroid hormone receptor beta, THRβ, shown to improve moderate to advanced hepatic fibrosis." (PMID 39394864, 2025). "In March 2024, the thyroid hormone receptor beta (THR-β) selective agonist resmetirom gained conditional approval from FDA as the first pharmacologic treatment for NASH patients with moderate-to-advanced liver fibrosis." (PMID 39925851, 2025). "Very recently, a study reporting on a phase 3 randomized controlled trial has suggested that resmetirom, an oral liver-directed thyroid hormone receptor beta-selective agonist, could improve (delay) the evolution of liver fibrosis in individuals with non-alcoholic steatohepatitis." (PMID 39456575, 2024). "The first approved thyroid hormone receptor beta (THR-β) agonist, resmetirom (Rezdiffra), is indicated for non-cirrhotic non-alcoholic steatohepatitis (NASH) patients with moderate to advanced liver fibrosis." (PMID 41415209, 2025). "In the NASH model, the combination of CS17919 and a THRβ agonist (CS27109) was found to significantly improve liver inflammation and substantially reduced liver fibrosis." (PMID 38873818, 2025). "Recently, a phase 3 trial reported that resmetirom, a thyroid hormone receptor beta (THR-β)-selective agonist, improved nonalcoholic steatohepatitis (NASH) or fibrosis resolution in NASH patients with liver fibrosis 6,7." (PMID 40083711, 2025). "In 2024, Food and Drug Administration approved the first drug, a thyroid hormone receptor beta–selective agonist, resmetiron, for the treatment of NASH with F2–3 liver fibrosis." (PMID 39470335, 2024). "Recently, Resmetirom (Rezdiffra, Madrigal Pharmaceuticals, Inc), a thyroid hormone receptor-beta (THRβ) agonist was approved for the treatment of non-cirrhotic MASH with moderate to advanced liver fibrosis." (PMID 40608687, 2025). "In early 2024, a new therapeutic option, Resmetirom, a liver-directed thyroid hormone receptor beta (THR-β) agonist, became available in the United States for individuals with MASH having moderate to advanced liver fibrosis (F2-F3), offering a targeted approach to treatment." (PMID 40970009, 2025). "Resmetirom, a thyroid hormone receptor-beta (THR-β) agonist, specifically targets liver function to simulate localized hyperthyroidism, effectively reducing lipid accumulation and liver fibrosis without the systemic effects commonly associated with thyroid hormone therapy." (PMID 40212963, 2025). "Rezdiffra, a novel thyroid hormone receptor-beta (THR-β) agonist, emerges as a beacon of hope for adults grappling with noncirrhotic MASH accompanied by moderate to advanced liver fibrosis (stages F2 to F3)." (PMID 41303369, 2025).
non-alcoholic steatohepatitis (16 papers, 2021 to 2026). "On 14th March 2024, the US Food and Drug Administration (FDA) granted approval to the first medication, resmetirom (an oral, liver-directed, thyroid hormone receptor beta–selective agonist) for metabolic dysfunction-associated steatohepatitis (MASH)." (PMID 39798849, 2025). "Based on a study, liver THRB expression negatively correlated with a severe nonalcoholic steatohepatitis in obese individuals who had undergone bariatric surgery." (PMID 36320063, 2022).
thyroid cancer (15 papers, 2012 to 2025). "Hereditary resistance to thyroid hormone is mainly determined by genetic variants in the thyroid hormone receptor beta (THRB) gene, which plays an essential role in repression of thyroid carcinoma." (PMID 37264363, 2023). "In the data from GSE53157, the downregulation of THRB mRNA was significantly associated with different types of thyroid cancers, including FTC, FVPTC, PDTC and PTC." (PMID 35681752, 2022). "In an animal study, mutation of THRB significantly increased the morbidity of spontaneous thyroid carcinoma through the activation of TSH-mediated signaling pathways." (PMID 25621029, 2015). "We found a gene–gene interaction of THRB with TG or TRHR for thyroid cancer susceptibility in the population studied." (PMID 23781307, 2012). "Nevertheless, it is important to replicate these results in other populations and evaluate other genetic variants of THRB to ascertain the implication of individual THRB polymorphisms in thyroid cancer susceptibility." (PMID 23781307, 2012). "Here, our results suggest the importance of genetic variants in THRB in combination with polymorphisms in other genes of the thyroid function (i.e. TG or TRHR) in determining thyroid cancer risk." (PMID 23781307, 2012). "On the other hand, the genotyped THRB SNP that maps in the hormone binding domain (rs3752874) has shown a combined effect with either the TG-rs2076740 or the TRHR-rs4129682 for thyroid cancer risk, and the interaction effect was more than multiplicative (Pinteraction<0.05 and <0.01 respectively)." (PMID 23781307, 2012). "An interaction effect between genetic variants of THRB and TG was found for thyroid cancer risk." (PMID 23781307, 2012). "Furthermore, this is the first study reporting on the analysis of the association of genetic variants in THRB with thyroid cancer." (PMID 23781307, 2012). "These actions of the reactivated THRB gene occurred through suppression of the β-catenin signaling pathway in thyroid cancer cell lines." (PMID 34761120, 2021). "Further, the promoter hypermethylation level of the THRB gene was positively correlated with thyroid cancer progression." (PMID 34761120, 2021). "Evaluation of thyroid cancer specimens of patients and cancer cell lines showed that the expression of the THRB gene was suppressed through its promoter hypermethylation." (PMID 34761120, 2021). "Therefore, another possible explanation for the combined effect of TG and THRB for thyroid cancer susceptibility could reside in the alteration of the transport of the thyroid hormone together with a decrease in the hormone receptor in the follicular cells of the thyroid gland." (PMID 23781307, 2012). "Given the functional relationship between THRA, THRB, TSHR and TRHR, we decided to evaluate the combined effect of common genetic variants of these genes on thyroid cancer susceptibility." (PMID 23781307, 2012). "Our results confirm that THRA is a risk factor for DTC, and we show for the first time the combined effect of THRB and TG or TRHR on DTC susceptibility, supporting the importance of gene–gene interaction in thyroid cancer risk." (PMID 23781307, 2012). "Furthermore, hypermethylation of the TRβ (thyroid hormone receptor beta) gene is prevalent in thyroid cancer, serving as an alternative mechanism for gene silencing." (PMID 40290121, 2025). "It was reported that a transgenic mouse model harboring a dominant-negative variant of THRB accelerated the metastasis of thyroid carcinoma indicating the role of THRB in carcinogenesis." (PMID 37264363, 2023). "When human thyroid cancer cell lines in which the THRB gene was silenced through its promoter hypermethylation were treated with demethylation agents, the THRB gene expression was reactivated, which suppressed cancer cell proliferation and migration, and in vivo tumor growth in a xenograft model." (PMID 34761120, 2021).
thyroid cancer (continued). "Additionally, ligand-bound thyroid hormone receptor beta (TRβ) was found to activate the RhoB signaling pathway upstream of p21 in thyroid cancer cells resulting in an inhibition of proliferation both in vitro and in vivo that required upregulation of RhoB." (PMID 29385717, 2018). "Moreover, decreased expression due to silencing of the THRB gene by promoter hypermethylation has been found in human cancer including breast, lung, and thyroid carcinoma." (PMID 25275301, 2014). "Given the limited information concerning the implication of genes involved in the thyroid function on thyroid cancer risk, in this study, we have analysed the risk association between common genetic variants in the THRA, THRB and TSHR genes and DTC in a large Spanish population." (PMID 23781307, 2012). "Although mutations in the TR genes, THRA and THRB, are not common in thyroid tumours, a decreased expression of these genes has been found in thyroid cancer." (PMID 23781307, 2012). "In the case of THRB, there is no reported data about THRB genetic variants related to the thyroid cancer risk." (PMID 23781307, 2012). "THRB has been reported to act as a transcription-suppressive factor in response to the changes in THs levels, lying at the crossroad of many cellular signaling pathways and playing a critical role in maintaining normal cell characteristics and tumor progression in thyroid cancer." (PMID 36293372, 2022). "Alterations in the genes of these receptors (THRA, THRB and TSHR) have been related to thyroid diseases, including thyroid cancer." (PMID 23781307, 2012). "As the THRB 3′-UTR is involved in the silencing of the THRB gene, we can speculate that genetic variants in the gene encoding the TG protein may produce a small variation in the function of the protein that, in combination with a decrease in the TR, would alter the susceptibility to thyroid cancer." (PMID 23781307, 2012). "Recent studies have suggested that molecules such as thyroid hormone receptor beta (THRβ) and Runt Related Transcription Factor 2 (RUNX2) may be involved in the mechanism responsible for calcification in thyroid cancer." (PMID 30049993, 2018). "THRB gene was shown to act as an oncogene in thyroid carcinomas, but not much is known about its possible role in colon cancer." (PMID 22879877, 2012).